TLR9 (toll like receptor 9)
Diseases named in the same sentence as TLR9 in open-access papers (continued):
Sharing a sentence is not in itself a finding about the gene and the disease.
endometrial cancer (6 papers, 2010 to 2024). Primary or metastatic malignant neoplasm involving the endometrium (mucous membrane that lines the endometrial cavity). "There is growing evidence showing the impact of TLR2 and TLR9 genetic polymorphisms on risk of gallbladder cancer, cervical cancer, non-Hodgkin lymphoma and endometrial cancer." (PMID 22309608, 2012). "Clearly, the association of these TLR9 polymorphisms and endometrial cancer risk must be further examined in an independent population." (PMID 20646321, 2010). "In the current study, we showed that the variant alleles of the TLR9 polymorphisms, rs5743836 (C allele) and rs187084 (C allele) combined, are associated with a decreased risk of endometrial cancer." (PMID 20646321, 2010). "Haplotype analysis revealed that the combination of the variant alleles of the two TLR9 polymorphisms, rs5743836 and rs187084, were protective for endometrial cancer risk: OR 0.11, 95% CI (0.03-0.44), p = 0.002." (PMID 20646321, 2010). "Haplotype analysis revealed that the combination of the variant alleles for TLR9 rs187084 and rs5743836 were associated with a significant decreased risk of endometrial cancer; TT vs CC: OR 0.11, 95% CI (0.03-0.44), p = 0.002." (PMID 20646321, 2010). "Kaplan-Meier survival analysis and T-tests were used to evaluate the influence of the NOD1, NOD2, TLR2, TLR4 and TLR9 polymorphisms on the age of diagnosis of endometrial cancer." (PMID 20646321, 2010). "The combination of the variant C alleles of TLR9 rs5743836 and rs187084 appears to be protective for endometrial cancer and that the high activity C allele of rs5743836 may allow a better response to pathogenic microbes that present in the endometrium." (PMID 20646321, 2010). "Higher TLR-9 transcriptional activity may be a protective factor for endometrial cancer risk." (PMID 30322386, 2018). "For these reasons, we sought to determine if genetic variation in a number of TLRs and NOD genes (TLR2, TLR4, TLR9, NOD1 and NOD2) were associated with risk of developing endometrial cancer." (PMID 20646321, 2010). "With respect to the TLRs, TLR2, TLR4 and TLR9 are highly polymorphic and represent interesting targets to elucidate their role in endometrial cancer development." (PMID 20646321, 2010). "Ten polymorphisms were genotyped in 191 endometrial cancer cases and 291 controls using real-time PCR: NOD1 (rs2075822, rs2907749, rs2907748), NOD2 (rs5743260, rs2066844, rs2066845), TLR2 (rs5743708), TLR4 (rs4986790) and TLR9 (rs5743836, rs187084)." (PMID 20646321, 2010).
fibrosis (6 papers, 2011 to 2022). the formation of excess fibrous connective tissue in an organ or tissue in a reparative or reactive process. "The strongest data that ties TLR9 activation to NASH disease is data from the Sanyal lab that directly associates TLR9 activation with NASH and fibrosis disease severity in human patients." (PMID 33584545, 2020). "However, the data supports that circulating mtDNA levels are significantly elevated in the vast majority of NASH and NASH-fibrosis patients who are obese, and TLR9 activation is significantly associated with disease severity in unenriched cohorts of NASH and NASH-fibrosis patients." (PMID 33584545, 2020). "When compared to naive recipients, ALT serum levels significantly increased (P< 0.01) following fibrosis, but were not much affected by the TLR9 lymphocyte background." (PMID 24340043, 2013). "Thus, we investigated whether forced (non-infectious) stimulation of TLR-9 in bleomycin-induced fibrosis might also be protective." (PMID 21810214, 2011).
Hypertension (6 papers, 2019 to 2025). The presence of chronic increased pressure in the systemic arterial system. "The TLR-9 inhibitor ODN2088 lowered systolic blood pressure in SHR, while the TLR-9 agonist ODN2395 aggravated hypertension in Wistar-Kyoto rats and SHR rats." (PMID 38425502, 2024). "Additionally, the Toll-like receptor 9 (TLR9) expressed in the endoplasmic reticulum of immune cells recognize mitochondrial DNA-derived cell-free unmethylated CpG dinucleotides, which are upregulated in patients with essential hypertension." (PMID 32852643, 2020).
IgA nephropathy (6 papers, 2011 to 2022). "The aim of this study was to determine the role of TLR9 in the immunopathogenesis of IgA nephropathy (IgAN) and membranoproliferative glomerulonephritis (MPGN) in the context of Epstein–Barr virus (EBV) infection." (PMID 36233099, 2022). "In another glomerulopathy, IgA nephropathy, common polymorphisms in several genes (MYH, TLR9) were associated with disease progression and development of ESRD." (PMID 25019165, 2014). "The profile of currently known genetic polymorphisms in TLR-9 has been proposed to associate with severe clinical phenotypes and TLR-9 polymorphisms appear to affect IgA nephropathy progression." (PMID 23472199, 2013). "The aim of this study was to determine the role of TLR9 in immunopathogenesis of IgA nephropathy (IgAN) and membranoproliferative glomerulonephritis (MPGN) as potentially diagnostically useful molecules and to review their role in EBV incidence in patients with GN." (PMID 36233099, 2022). "The important roles of TLR4 and TLR9 in IgAN have been studied by several groups, pointing out that their expression was associated with disease severity and even the pathogenesis of IgAN, but the underlying mechanism of how TLRs led to the pathogenesis of IgA nephropathy is not fully elucidated." (PMID 29403161, 2017).
lymph node metastasis (6 papers, 2015 to 2024). "The presence of lymph node metastases was associated with a higher prevalence of CC variant genotype of TLR9 rs187084 polymorphism compared to the major TT genotype (P ═ 0.020) and compared to T-allele carriers (combined TT + CT), P ═ 0.015." (PMID 38850110, 2024). "Patients with lymph node metastases had higher frequencies of the TLR9 rs187084 CC variant genotype compared to the major TT genotype (P ═ 0.020) and to T-allele carriers (combined TT + CT genotypes, P ═ 0.015)." (PMID 38850110, 2024). "High level of TLR9 expression was shown to be significantly associated with higher probability of lymph node metastasis, preoperative PSA and Gleason score." (PMID 26087186, 2015). "Here, we found that high expression of TLR9 was associated with a higher probability of lymph node metastasis and poor prognosis." (PMID 26087186, 2015). "Our results suggest that OSCC patients with the variant CC genotype or C allele carriers (CT+CC genotypes) of the TLR9 rs187084 polymorphism have a higher risk of lymph node metastasis and advanced tumor stage, as well as a reduced OS, compared to patients with the TT genotype." (PMID 38850110, 2024). "The TLR9 − 1486 CC genotype increased the susceptibility of NPC in the Chinese population and patients with this genotype were inclined to advanced tumor stage and lymph node metastasis." (PMID 32753695, 2020). "Only 2 cases (4.08%) were positive lymph node metastasis in the 49 cases with low TLR9 expression." (PMID 26087186, 2015). "Moreover, 7 cases (24.14%) were positive lymph node metastasis in the 29 cases with high TLR9 expression." (PMID 26087186, 2015). "Of the 95 lymph node metastases, analyzable samples were available for 70 (TLR1), 72 (TLR2), 77 (TLR4), 58 (TLR5), 76 (TLR6), 72 (TLR7), 76 (TLR8) and 70 (TLR9) cases." (PMID 38709790, 2024).
lymphopenia (6 papers, 2014 to 2024). Reduction in the number of lymphocytes. "The loss of TLR7 in the B cell is sufficient to suppress several of the hallmark cellular manifestations of SLE in Tlr9–/– MRL/lpr mice, including T cell activation and B cell lymphopenia." (PMID 37606042, 2023). "A significantly lower count of CD4+ cells with TLR9 was observed in patients with lymphopenia, compared with patients with a normal lymphocyte count (>1000/mm3) in the peripheral blood (4.59% ± 5.83 versus 6.86% ± 6.83 resp., P < 0.005)." (PMID 24692849, 2014). "However, it cannot be excluded that the differences in TLR9 expression between these two subgroups (lymphopenia and hypogammaglobulinemia) may be caused by the different numbers of patients receiving immunosuppressive drugs, the number being lower in the case of hypogammaglobulinemia." (PMID 24692849, 2014). "Similarly, topical application of a TLR9 agonist, CpG oligodeoxynucleotides (ODNs), neither changed monocyte counts nor caused lymphopenia." (PMID 37566453, 2023).
meningococcal meningitis (6 papers, 2012 to 2024). "Another study, performed to analyze the involvement of TLR9 2848 SNP in susceptibility to meningococcal meningitis, also showed similar frequencies of GG, GA and AA genotypes, with the highest occurrence of heterozygotes." (PMID 25844529, 2015). "We recently described an association of single nucleotide polymorphisms (SNPs) in TLR9 with susceptibility to meningococcal meningitis (MM)." (PMID 22662111, 2012). "We recently reported an association of single nucleotide polymorphisms (SNPs) in TLR9 with susceptibility to meningococcal meningitis (MM)." (PMID 22662111, 2012). "Endosomal TLR9 was reported to play an important part in immune cell activation upon exposure to N. meningitidis suggesting a potentially beneficial effect of hydroxychloroquine in meningococcal meningitis." (PMID 38678151, 2024).
oral cancer (6 papers, 2020 to 2024). "Thus, it seems that the activation of TLR9 is closely linked to oral cancer prognosis, which implies that the inhibition of TLR9 seems to be a targeting point of future investigation." (PMID 38850110, 2024). "However, there are limited data on the association between TLR7 and TLR9 polymorphisms and prognosis or susceptibility to oral cancer or other subtypes of HNSCC, such as nasopharyngeal carcinoma (NPC)." (PMID 38850110, 2024). "In any case, our results open up new avenues to investigate the possible interaction between consumption habits and immune characteristics of oral cancer and provide new evidence to consider TLR9 as a therapeutic target in OSCC." (PMID 35990685, 2022). "The oral cancer cell supernatant was observed to reduce TLR9 mRNA expression and inhibit TLR9-mediated IFNα production in human peripheral blood pDCs through a TGFβ and IL-10 dependent mechanism." (PMID 33919546, 2021). "A study on TLR9 polymorphisms rs5743836, rs352140, rs187084, and rs352139 in OSSC patients found that all investigated variants could increase the oral cancer risk and potentiate bacterial gingival inflammation/gingival recession." (PMID 38850110, 2024). "Since oral cancer is closely associated with HPV infection, TLR7 and TLR9 as endogenous sensors of viral nucleic acids may play a significant role in the malignant transformation in OSCC." (PMID 38850110, 2024). "TLR9 and TLR7 polymorphisms could potentially have a role in the modulation of immune responses to alcohol-associated DAMPs, and the impaired initiation of anti-tumor immune response in oral cancer." (PMID 38850110, 2024).
prostate tumor (6 papers, 2013 to 2025). "We, therefore, decided to inquire further into the role of TLR9 activation and its effect on immune cells, which could be causing the reduction of prostate tumor size." (PMID 38201300, 2024). "The results of another study are similar to our findings and those of Väisänen, indicating that elevated TLR-9 expression is observed in prostate tumours with higher GS." (PMID 39201739, 2024). "Further studies are needed to examine the temporal changes in prostate tumor composition driven by TLR9 stimulation in this model, and how “stimulated” immune cells function during early tumor development." (PMID 38201300, 2024). "Our control study and the published results in prostate tumor models confirmed that concomitant TLR9 activation and STAT3 inhibition are necessary for the generation of effective antitumor effects." (PMID 38259453, 2023). "To evaluate TLR9 effect on prostate tumor progression, we injected LNCaP, LNCaP-S17 and PC3 cell variants subcutaneously into immunodeficient NSG mice." (PMID 26046794, 2015). "The proof-of-principle experiments using CpG-siRNAs to target tumorigenic NF-κB/RELA and STAT3 signaling in xenotransplanted TLR9+ prostate tumors confirmed therapeutic efficacy of such strategy." (PMID 26046794, 2015). "Vaccination of mice with a DNA vaccine encoding the ligand-binding domain of the androgen receptor, a prostate tumor associated antigen, and combined with TLR3 and TLR9 agonists, resulted in secretion of type 1 IFN from antigen-presenting cells and suppression of TRAMP-C1 prostate tumor growth." (PMID 41012179, 2025). "As such, the combined inhibition of STAT3, a protumorigenic signal activated in TLR9-stimulated tumor cells, with CPG-ODNs led to the suppression of subcutaneous or intratibial castrate-resistant prostate tumors in mice." (PMID 38201300, 2024). "It is possible that the T cells infiltrating prostate tumors contribute to tumor maintenance rather than its suppression, and that systemic TLR9 stimulation alters this effect." (PMID 38201300, 2024).
acute myeloid leukemia (5 papers, 2020 to 2022). Acute myeloid leukemia (AML) is a group of neoplasms arising from precursor cells committed to the myeloid cell-line differentiation. "With respect to neoplastic diseases, acute myeloid leukemia (AML), and cervical cancer were also associated with TLR9 genetic variants, while rs187084 is proposed to be a prognostic factor in patients with prostate cancer." (PMID 33763088, 2021). "In addition, the current findings indicate that the identification of patterns of genetic variations, in the form of the C-G-A haplotype of TLR9 rather than the TLR9 single nucleotide polymorphism, may represent a promising approach to predict the risk for developing acute myeloid leukemia." (PMID 35330409, 2022). "In other hematological cancers, such as acute myeloid leukemia (AML), the mRNA expression levels of TLR2 and TLR4, but not of TLR9, were increased, contrary to what was observed in ALL, and expression of TLR7 and 9 was decreased in chronic myeloid leukemia (CML)." (PMID 34567117, 2021).
anthrax (5 papers, 2014 to 2023). "The current study demonstrates that BAG during anthrax infection is recognized by TLR9 and this recognition stimulates TNF-α production via MAPK and NF-κB pathways in mouse macrophages." (PMID 25472474, 2014). "Based on these observations, we postulated that BAG and other virulence factors during anthrax infection are recognized by TLR9 and their corresponding receptors, which induce TNF-α production via MAPK and NF-кB signaling pathways." (PMID 25472474, 2014). "Our results suggest that B. anthracis DNA may contribute to anthrax pathogenesis by enhancing LT activity via TLR9-mediated TNF-α production." (PMID 25472474, 2014). "AV7909 (NuThraxTM) is a next-generation anthrax vaccine composed of the currently licensed BioThrax® adjuvanted with the CPG 7909 compound, a Toll-like receptor 9 (TLR9) agonist." (PMID 32365729, 2020).
aspergillosis (5 papers, 2014 to 2023). Aspergillosis is an infection, growth, or allergic response caused by the Aspergillus fungus. "Of note, several polymorphisms of human TLRs, e.g., TLR1, TLR2, TLR4, TLR6, or TLR9, have been associated with increased risk of invassive aspergillosis in susceptible hosts." (PMID 29081774, 2017). "In the same study, a SNP in TLR9 was shown to predispose to the allergic form of pulmonary aspergillosis." (PMID 25266752, 2014). "The previous studies showed that the elimination of aspergillosis occurs by phagocytosis involving the Toll-like receptor 9-BTK-calcineurin-nuclear factor of T cell pathway." (PMID 32333154, 2020). "Suggesting that, although TLR9 activation plays a different role, depending on the cell analyzed, its absence generates a protective response against aspergillosis." (PMID 33194839, 2020). "Several researchers have shown a significant association between TLR4 and/or TLR9 SNPs and the incidence of several forms of aspergillosis; however, another study failed to associate these polymorphisms with that disease." (PMID 25266752, 2014).
candidiasis (5 papers, 2012 to 2025). Infection with the organism Candida. "In contrast, single TLR7 or TLR9 deficiency had a less pronounced effect, highlighting a synergistic role for these receptors in host defense.For instance, in a murine model of Candida infection, TLR9-deficient mice demonstrated increased fungal loads and diminished survival rates." (PMID 41459537, 2025). "However, a lower fungal dose leads to increased susceptibility to systemic candidiasis and impaired fungal clearance in TLR9−/− mice, indicating that the fungal load may determine the role of TLR9 during infection." (PMID 23189270, 2012). "A recent study demonstrated that a wild-type strain of Candida induced TLR2, TLR4, TLR6, and TLR9 gene expression activation in the epithelial cells showing that different receptors may play important roles in candidiasis." (PMID 32466609, 2020).
Cerebral ischemia (5 papers, 2009 to 2023). Restriction of arterial blood supply to the brain associated with insufficient oxygenation to support the metabolic requirements of the tissue. "Although the central nervous system is a sterile circumstance and no pathogens such as germs or viruses exist under normal or ischemic condition, it is found that cerebral ischemia causes elevation in the expression of TLR2, TLR4, and TLR9 in neurons." (PMID 23864765, 2013). "Recognition that TLR9 is a new target for preconditioning broadens the range of potential antecedent therapies for brain ischemia." (PMID 21982558, 2011). "Recently TLR9 was shown to induce tolerance to brain ischemia." (PMID 21982558, 2011). "Recently, TLR4 and TLR9-induced tolerance to cerebral ischemia has been well studied." (PMID 21982558, 2011). "Unmethylated cytosine-guanine rich oligodinucleutides (CpG ODNs), which act on Toll-like receptor 9 (TLR9), have been shown to be a highly effective means of prophylactic neuroprotection in a mouse model of cerebral ischemia." (PMID 20190963, 2009). "Clinical studies have shown that the expression of TLR3 and TLR9 in the peripheral blood of patients with ischemic stroke has nothing to do with nerve damage, which further indicates that TLR3 and TLR9 are not directly involved in the regulation of cerebral ischemia-reperfusion inflammation damage." (PMID 35008558, 2021).
chronic obstructive pulmonary disease (5 papers, 2011 to 2025). A chronic and progressive lung disorder characterized by the loss of elasticity of the bronchial tree and the air sacs, destruction of the air sacs wall, thickening of the bronchial wall, and mucous accumulation in the bronchial tree. "TLR-9-positive septal cells were increased during the chronic obstructive pulmonary disease as compare to normal human lungs." (PMID 27956782, 2016).
Cognitive impairment (5 papers, 2019 to 2025). Abnormal cognition is characterized by deficits in thinking, reasoning, or remembering. "With compromised TLR9 function, this fundamental memory mechanism becomes a gateway to genomic instability and cognitive impairments implicated in accelerated senescence, psychiatric disorders and neurodegenerative disorders." (PMID 38538785, 2024). "Elevated TLR signaling through TLR2, TLR4, and TLR9 correlates with frailty, cognitive impairment, and functional decline." (PMID 41373468, 2025).